TLR7 (toll like receptor 7)
Diseases named in the same sentence as TLR7 in open-access papers (continued):
Sharing a sentence is not in itself a finding about the gene and the disease.
head and neck squamous cell carcinoma (3 papers, 2020 to 2024). A squamous cell carcinoma that arises from any of the following anatomic sites: lip and oral cavity, nasal cavity, paranasal sinuses, pharynx, larynx, and salivary glands. "In head and neck squamous cell carcinoma (HNSCC), a combination of intratumoral injections of TLR7 and TLR9 agonists with PD-1 blockade suppresses tumor growth and promotes systemic adaptive immunity." (PMID 38732254, 2024). "In a study with late advanced head and neck squamous cell carcinoma (HNSCC) patients, 42.9% of the patients had an increase in TLR7 levels." (PMID 36476317, 2022).
heart failure (3 papers, 2019 to 2023). Inability of the heart to pump blood at an adequate rate to meet tissue metabolic requirements. "MRNA levels of three candidate genes (Ccr5, Csf1r, and Tlr7) were significantly increased in heart failure mice." (PMID 38104081, 2023). "As an agonist of TLR7, abnormal accumulation of 2′,3′-cGMP could contribute to the inflammatory and fibrotic responses in the pathophysiology of heart failure." (PMID 34639145, 2021). "However, we cannot exclude the possibility that TLR7/8 is involved in the effect of E6446 on the development of heart failure." (PMID 31312759, 2019).
itch (3 papers, 2014 to 2019). "One study found that Tlr7-/- mice showed deficits in IMQ evoked itch and proposed that Tlr7 expressed in dorsal root ganglion (DRG) neurons was mediating IMQ transduction." (PMID 29561265, 2018). "Imiquimod, a synthetic TLR7 agonist, was found to trigger inward currents and action potentials in TLR7+ sensory neurons and induce an itch-specific response." (PMID 25139109, 2014). "While our results demonstrate that TLR7 is not involved in transducing IMQ-evoked itch in the zebrafish, investigating the role of immune responses in mediating somatosensations (both in zebrafish and other species) would be an interesting route for future exploration." (PMID 29561265, 2018).
juvenile dermatomyositis (3 papers, 2018 to 2022). Juvenile dermatomyositis (JDM) is the early-onset form of dermatomyositis (DM), a systemic, autoimmune inflammatory muscle disorder, characterized by proximal muscle weakness, evocative skin lesion, and systemic manifestations. "In juvenile dermatomyositis, immature transitional B cells are expanded in patients with active disease and have an inflammatory phenotype with high interferon alpha and TLR7-pathway signals." (PMID 33468230, 2021).
kidney damage (3 papers, 2021 to 2023). "These researchers found that TLR7 proteins were abundant in CD19+ B cells infiltrating the kidneys of patients with IgAN, and inhibition of TLR7 in B cells reduced renal inflammation and nephropathy." (PMID 37596656, 2023).
leprosy (3 papers, 2018 to 2023). Leprosy is a chronic infectious disease affecting primarily the skin and peripheral nervous system. "Future research is needed to evaluate the potential significance of the distinct phenotypes observed in the TLR7/9 expressions within the pDCs of NR and ENL in leprosy immunopathogenesis." (PMID 35733868, 2022).
leukopenia (3 papers, 2009 to 2025). "In the light of these facts it was logical to hypothesize, that leukopenia would be a possible cause for the observed synergistic action of IAV and S. pneumoniae, more so, as TLR7 would provide a valuable mechanistic link." (PMID 19290047, 2009). "Functional studies link genetic variation with impact as rs2302267/n.−20T >G, which may protect from leukopenia through reduced TLR7 promoter activity, rs3853839/c.∗881 C >G-3’UTR increases TLR7 mRNA stability, thereby enhancing gene expression and IFN signaling." (PMID 41410901, 2025).
lung diseases (3 papers, 2020 to 2024). "This study provides evidence that TLR7 plays an important role in regulating MDSCs in lung diseases caused by S. japonicum infection." (PMID 36279265, 2022). "Because all of these benefits occur without evidence of overt toxicity, we conclude that targeted delivery of TLR7 agonists has the potential to treat fibrotic lung diseases with limited side effects." (PMID 32597014, 2020).
lupus-like syndrome (3 papers, 2012 to 2024). "Several lines of evidence support the conclusion that Tlr7 reactivation is a major contributor to the lupus-like syndrome of Ftx−/− females." (PMID 38701219, 2024).
measles (3 papers, 2008 to 2026). A highly contagious viral infection caused by the measles virus. "Polymorphisms of TLR7 and TLR8 have been shown to impact the clinical course of measles, but it remains to be tested how ChrX mosaicism for TLR variants impacts outcome after these virus infections." (PMID 29180997, 2017). "TLR7 plays an important role in the recognition and subsequent signaling of single-stranded RNA from viruses including influenza, measles, and dengue." (PMID 29180997, 2017).
meningitis (3 papers, 2014 to 2024). A disorder characterized by acute inflammation of the meninges of the brain and/or spinal cord. "The TLR7 overexpression-induced model showed NF-κB activation and proinflammatory cytokine production, while TLR7 silencing suppressed inflammatory reactions and apoptosis and promoted cell viability, reducing brain damage caused by meningitis in mice." (PMID 38891900, 2024). "However, a previous study on mouse meningitis induced by E. coli showed that TLRs were activated in brain tissues, with elevated Tlr2, Tlr4 and Tlr7 expression." (PMID 32509459, 2020). "A previous study has shown enhanced neuroinflammation following TLR9 agonist administration and suggested a role of normal TLR7, and potentially TLR 8 signaling, in modulating TLR9 related meningitis and neuroinflammation." (PMID 25229618, 2014).
myelodysplastic syndrome (3 papers, 2019 to 2025). A clonal hematopoietic disorder characterized by dysplasia and ineffective hematopoiesis in one or more of the hematopoietic cell lines. "There may also be an element of bone marrow (BM) failure contributing to the TLR7-induced phenotype (which lends itself to a diagnosis of a myelodysplastic syndrome)." (PMID 31998321, 2019).
myeloma (3 papers, 2013 to 2021). "Co‐expression of TLR1, TLR7 and TLR9 in myeloma cells has shown to be involved in induction of drug resistance." (PMID 33336901, 2021). "Analysis of toll-like receptor (TLR) expression at protein level indicated that TLR1, TLR3, TLR4, TLR7, TLR8, and TLR9, were similarly expressed in most human myeloma cell lines, including L363 and RPMI 8226 cells, as well as in primary cells from MM patients." (PMID 28702457, 2017). "Expression of mRNA for TLR1, TLR3, TLR4, TLR5, TLR7, TLR8, and TLR9 was found in all myeloma cell, but levels of mRNA expression differed amongst different cell lines." (PMID 23593278, 2013).
neutropenia (3 papers, 2009 to 2026). A decrease in the number of neutrophils found in the blood. "By contrast, only 1 of 12 TLR-7–deficient patients with critical disease developed neutropenia and 5 had a high ANC." (PMID 36880831, 2023).
pancreatic ductal adenocarcinoma (3 papers, 2019 to 2023). An infiltrating adenocarcinoma that arises from the epithelial cells of the pancreas. "We demonstrate that TLR7/8 agonist R848 induces anti-tumor responses and attenuates cachexia in murine models of pancreatic ductal adenocarcinoma (PDAC)." (PMID 31615993, 2019). "TLR7 is overexpressed in more than 50% of primary human pancreatic ductal adenocarcinoma (PDAC)." (PMID 36602302, 2023). "Cox regression survival analysis of patients with pancreatic ductal adenocarcinoma related to clinicopathological characteristics and TLR1, TLR3, TLR5, TLR7, and TLR9 immunoexpression." (PMID 31314777, 2019).
renal fibrosis (3 papers, 2021 to 2025). A final common manifestation of a wide variety of chronic kidney diseases characterized by glomerulosclerosis and tubulointerstitial fibrosis. "TLR7 deficiency protected against AD-induced tubular damage, inflammation, and renal fibrosis." (PMID 37596656, 2023). "In this study, we demonstrated that the activation of TLR7 in renal tubule epithelial cells by miR-21 contributes to inflammation in a renal fibrosis model." (PMID 37596656, 2023). "When the TLR7 inhibitor, M5049, was administered to the AD-induced renal fibrosis model, TLR7 inhibition significantly attenuated AD-induced renal inflammation and fibrosis." (PMID 37596656, 2023). "Overall, activation of TLR7 by endogenous miR-21 in renal epithelial cells contributes to inflammatory responses in a renal fibrosis model, suggesting a possible therapeutic target for the treatment of renal fibrosis." (PMID 37596656, 2023). "We further observed an increase in TLR7 expression following exposure to LPS, providing evidence for the role of TLR7 in inflammation, which is likely contributing to renal fibrosis development." (PMID 37596656, 2023). "Overall, our results suggest that activation of TLR7 by endogenous miR-21 contributes to inflammatory responses in a renal fibrosis model, suggesting a possible therapeutic target for the treatment of renal fibrosis." (PMID 37596656, 2023). "As the role of TLR7 activation in a kidney fibrosis model has not been investigated, IHC was employed to check the expression of TLR7 to determine its role in renal fibrosis." (PMID 37596656, 2023). "Collectively, our data suggest that the activation of TLR7 by endogenous miR-21 in renal epithelial cells contributes to the inflammatory responses in a renal fibrosis model, suggesting a possible therapeutic target for the treatment of renal fibrosis." (PMID 37596656, 2023). "Together, our data suggest that activation of TLR7 by endogenous miR-21 in renal epithelial cells contributes to the inflammatory responses in a renal fibrosis model, suggesting a possible therapeutic target for the treatment of renal fibrosis." (PMID 37596656, 2023). "Although TLR7 is known to promote inflammatory responses in pathophysiological conditions, its role in renal fibrosis has not been investigated." (PMID 37596656, 2023). "Expression of TLR-9 but not TLR-7 in renal tissue post-IRI was inhibited by HCQ, and the results are consistent with our previous study showing that depletion of TLR-9 attenuated renal fibrosis." (PMID 33936063, 2021).
respiratory infection (3 papers, 2017 to 2025). "Sex-based differences in the severity of RSV respiratory infections have been noted, and this may be related to higher expression of X-linked toll-like receptor 7 (TLR7) in female immune cells." (PMID 40143355, 2025). "We determined whether L. mucosae 1025, B. breve CCFM1026, and MIX affect the TLR7 signaling pathway in influenza A virus-respiratory infection." (PMID 33924002, 2021).
schizophrenia (3 papers, 2012 to 2026). A major psychotic disorder characterized by abnormalities in the perception or expression of reality. "In this study, we characterized the expression profiles of tRNA halves, potential contributors to cytokine elevation via the TLR7 axis, in olfactory epithelial (OE) cells derived from individuals with schizophrenia and matched healthy controls." (PMID 41542771, 2026). "All four examined 5′-tRNA halves were significantly upregulated in OE cells from schizophrenia, including the potent TLR7-stimulating species 5′-halfHisGUG and 5′-halfValCAC/AAC." (PMID 41542771, 2026). "However, despite the fact that some of the prenatal infectious agents most strongly linked to schizophrenia risk (rubella virus and influenza virus) are ss-viruses, models of maternal immune infection with ss-virus mimetics such as resiquimod or imiquimod, which stimulate TLR7/816,17 are rarer." (PMID 34903784, 2021). "Endosomal Toll-like receptor 7 (TLR7), which senses short noncoding RNAs (sncRNAs) as its ligands, mediates cytokine induction in microglia and is upregulated in schizophrenia." (PMID 41542771, 2026).
stomach adenocarcinoma (3 papers, 2021 to 2022). "Therefore, TLR7 can be used as a novel diagnostic biomarker, progression and prognostic indicator, and immunotherapeutic target for stomach adenocarcinoma." (PMID 36476317, 2022). "TLR7 could serve as diagnostic biomarkers, prognostic indicatiors, and immunotherapeutic targets of stomach adenocarcinoma." (PMID 33982398, 2021). "Our previous study also identified TLR7 as a candidate gene for stomach adenocarcinoma (STAD) via the WGCNA algorithm, and this could help predict the progression and prognosis of STAD and shed new light on its immunotherapy." (PMID 34490033, 2021). "Overexpression of TLR7 in patients with advanced stomach adenocarcinoma (STAD) indicates a higher degree and poorer prognosis." (PMID 36476317, 2022).
vasculitis (3 papers, 2014 to 2024). "Various TLRs, including TLR3 and TLR7 had been found upregulated in IgA vasculitis; this suggests their possible involvement in the pathogenesis of the vasculitis." (PMID 37500944, 2024).
alcoholic hepatitis (2 papers, 2019 to 2025). Acute hepatitis resulting from ingestion of alcohol. "The study also explored the association of TLR-7 with human alcoholic hepatitis using RNA sequencing data of human liver tissue and found that mRNA expression of TLR-7 was increased by more than 300% in patients with alcoholic hepatitis." (PMID 41614812, 2025). "A recent study using ethanol (25% w/v) feeding to stimulate alcoholic hepatitis showed that activation of TLR7 significantly upregulated expression of pro-inflammatory cytokines and the endogenous TLR-7 agonist let-7b from hepatocytes, hence exacerbating hepatic inflammation." (PMID 31717860, 2019).
alcoholism (2 papers, 2017 to 2021). "Let-7, a miRNA in our study, has also been observed in inflammatory processes to act via TLR-7 regulation in alcoholism." (PMID 35126468, 2021). "Our findings suggest that recurrent TLR7 activation by ethanol-induced microglial let-7 and HMGB1 release contributes to the progressive neurodegeneration associated with alcoholism." (PMID 28118842, 2017). "To assess the involvement of TLR7 and microglia in the pathology of alcoholism, we obtained frozen hippocampal tissue of postmortem human alcoholics from the New South Wales (NSW) Brain Tissue Bank." (PMID 28118842, 2017). "The correlation of TLR7 expression with lifetime consumption of alcohol suggests a role of TLR7 signaling in the pathology of alcoholism." (PMID 28118842, 2017). "Thus, the neuropathology of human alcoholism involves increased expression of TLR7, HMGB1, and microglial CD11b." (PMID 28118842, 2017). "TLR7 activation by alcohol in humans may contribute to the neuropathology of alcoholism." (PMID 28118842, 2017). "We identify a role of let-7 in the pathology of alcoholism that involves inter-cellular signaling through TLR7, rather than its intracellular function involving mRNA stabilization." (PMID 28118842, 2017). "However, a role for TLR7 in alcoholism has not been described." (PMID 28118842, 2017).
anthrax (2 papers, 2018 to 2020). "Alum/TLR7 is currently in phase I clinical development and has been tested in several disease models, such as in the context of staphylococcus, anthrax, meningococcal meningitis infections." (PMID 32131853, 2020). "In preclinical studies, Alum/TLR7 showed a superior adjuvant capacity, compared to Alum, in several disease models, such as meningococcal meningitis, anthrax, staphylococcus infections." (PMID 29686670, 2018).
autoimmune hepatitis (2 papers, 2018 to 2021). Hepatitis caused by autoantibodies. "The inhibitory effect of the anti-TLR7 was also observed in vivo, rescuing Unc93b1D34A/D34A mice from TLR7-dependent autoimmune hepatitis." (PMID 34868046, 2021).
cerebral malaria (2 papers, 2014 to 2019). A sequestration of Plasmodium falciparum in the brain, which can cause coma and/or seizures. "The single-stranded RNA(ssRNA) sensor TLR7 has been reported to act as an early sensor of plasmodium infection, and TLR7-deficient mice are partially protected from cerebral malaria." (PMID 30972055, 2019). "This study sought to clarify the role of Toll-like receptors (TLRs) in promoting immunopathology associated with cerebral malaria, with a particular focus on the understudied TLR7." (PMID 25192715, 2014). "Loss of TLR7 conferred partial protection against fatal experimental cerebral malaria." (PMID 25192715, 2014). "However, in contrast to findings with TLR9- and MYD88-deficient mice, in the only study to examine the role of TLR7-deficiency in cerebral malaria, TLR7 was found to be irrelevant for precipitation of fatal disease." (PMID 25192715, 2014). "The loss of both TLR7 and TLR9 signalling leads to cytokine dysregulation during the course of P. berghei ANKA infection and protects against symptoms of cerebral malaria." (PMID 25192715, 2014). "As expected, Tlr7-/-Tlr9-/- mice demonstrated improved survival as compared to wild-type mice, with 24% escaping cerebral malaria." (PMID 25192715, 2014). "This work identifies signalling through TLR7 as a source of pathology in experimental cerebral malaria." (PMID 25192715, 2014). "In the current study, the experimental hazard ratio between B6 and Tlr7-/- mice was determined to be 2.847, with a probability of 0.888 that a subject of either genotype would succumb to cerebral malaria by the end of the experiment." (PMID 25192715, 2014). "In this highly powered study, it has been shown that signalling through TLR7 contributes to lethality from cerebral malaria." (PMID 25192715, 2014). "in a previous work, it was hypothesized that TLR7 might play a role in the pathology of P. berghei cerebral malaria that was previously undetected." (PMID 25192715, 2014). "This study was performed using small cohorts of mice in an experimental design intended to screen several candidate strains, which allowed for the possibility that a role for TLR7 in cerebral malaria may have been overlooked." (PMID 25192715, 2014). "Interestingly, one study reported that mice overexpressing TLR7 were also partially protected from cerebral malaria." (PMID 25192715, 2014). "Notably, similar to the protection seen in TLR7-deficient mice, TLR7 overexpression did not have any effect on parasite load, indicating that this protection is a consequence of increasing host tolerance to cerebral malaria without affecting host resistance." (PMID 25192715, 2014). "The simplest interpretation of these data is that TLR7 and TLR9 synergistically signal to promote cerebral malaria, with both sensors being required for full elaboration of lethal pathology (and conversely, loss of both sensors not conferring more protection than loss of either sensor alone)." (PMID 25192715, 2014). "The current findings demonstrate that the absence of TLR7 during experimental cerebral malaria shifts the balance of cytokines towards an anti-inflammatory state and confers protection from cerebral malaria lethality." (PMID 25192715, 2014). "Importantly, unlike the synergistic interaction between TLR7 and TLR9 suggested by the survival data, these results are consistent with a model in which TLR7 and TLR9 signal redundantly through MYD88 to promote cytokine production during experimental cerebral malaria." (PMID 25192715, 2014).
cervical intraepithelial neoplasia (2 papers, 2010 to 2024). "This study investigates the therapeutic potential of imiquimod (IMQ), a synthetic toll-like receptor 7 agonist, for treating cervical intraepithelial neoplasia (CIN) associated with human papillomavirus (HPV) infection." (PMID 38610950, 2024).
cholangiocarcinoma (2 papers, 2021 to 2022). A carcinoma that arises from the intrahepatic biliary tree (intrahepatic cholangiocarcinoma) or from the junction, or adjacent to the junction, of the right and left hepatic ducts (hilar cholangiocarcinoma). "In our study, we demonstrate that both TLR7 and TLR9 expression are associated with a favorable prognosis in our cohort of cholangiocarcinoma patients." (PMID 34573939, 2021).